IL6 (interleukin 6)
Diseases named in the same sentence as IL6 in open-access papers (continued):
Sharing a sentence is not in itself a finding about the gene and the disease.
breast cancer (continued). "Cytokines such as interleukin-6 (IL-6), oncostatin M (OSM), and interleukin-1 beta (IL-1β) promote the development of both acute and chronic inflammation while promoting in vitro metrics of breast cancer metastasis." (PMID 31007849, 2019). "This then inhibits NF-κB-dependent production of IL-6, STAT3 activation, and IL-6/STAT3-driven cell migration and invasion of breast cancer cells, thereby establishing an IL-6/STAT3/NF-κB/miR-146a negative feedback loop." (PMID 31557902, 2019). "The subcellular localization of ANRIL and whether it correlates with IL6, CCL2, and POSTN expression, found in other conditions, in breast cancer is also unknown." (PMID 31572679, 2019). "Indeed, studies have demonstrated that IL-6 and its downstream signaling transcription factor, STAT3, are essential for the formation and progression of liver cancer, lung cancer, breast cancer, and leukemia." (PMID 31174326, 2019). "Recently, increasing studies have demonstrated that MSCs within the tumor stroma may promote breast cancer progression by secreting cytokines such as CCL5, IL-6, or TGF-β." (PMID 30795783, 2019). "MCT-1 stimulated IL-6/Stat3 signaling, suggesting that MCT-1 may also stimulate the NO/NOTCH pathway to mediate breast cancer metastasis and recurrence." (PMID 30885232, 2019). "Next, we examined whether AICAR-induced AMPK activation could mimic MTF reduction of IL-6-induced phosphorylation of STAT3 and NF-κB in MBCDF and MBCD17 breast cancer cells." (PMID 31337349, 2019). "In breast cancer cells, CaSR inhibited IL-6 secretion, while LPA and S1P enhanced IL-6 expression." (PMID 31847214, 2019). "In CD44+ CD24− basal-like breast cancer cells—indicative of a stem cell-like phenotype—the overactivation of STAT3 correlated with low metastasis-free survival and the induction of pro-invasive chemokines, IL-6, and TGF-β signaling." (PMID 31842362, 2019). "However, our results for let-7-5p are in agreement with those observed for let7, let-7a, and let-7d that down-regulate IL-6 and IL-10 directly or TNF, IL-6, and IL-1β indirectly in MCF10A, fibroblasts, and breast cancer cells." (PMID 31694049, 2019). "Moreover, in high-IL-6-secreting MDA-MB-231 breast cancer cells, HIC1 was restored upon knocking down IL-6 expression, accompanied by decreased STAT3 activity." (PMID 31795965, 2019). "Furthermore, these results demonstrate that not only does high expression of each one of these cytokines increase metastasis and decrease survival in breast cancer patients, but OSM and IL-1β also induce the expression of IL-6." (PMID 31007849, 2019). "RT-qPCR of breast cancer cells after 3 days of transwell co-culture with control shRNA obASCs or leptin shRNA obASCs shows an increase in expression of CCL5, CD90, PTGS2, and IL-6 after co-culture with obASCs that is abrogated by leptin shRNA in the obASCs." (PMID 31118047, 2019). "In breast cancer, studies have begun to identify the mechanisms by which adipocyte-induced EMT occurs, among the identified pathways are the TGF-β/Smad axis, TGF-β/STAT3 axis and the IL-6/STAT3 axis." (PMID 31383893, 2019). "Both IL-6 and Osm have been reported to inhibit MCF-7 cell growth in breast cancer." (PMID 31358059, 2019). "Moreover, toxicity against breast cancer cells strongly correlated with cytokine inhibition with p = 0.023 for IL-1β and p < 0.001 for TNF-α, IL-6, IL-8, and IL-10." (PMID 31581678, 2019). "MBCDF and MBCD17 primary breast cancer cell lines were seeded at 15000 cells/cm2 in a 24-well plate and incubated under the absence (control) or presence of IL-6 10 ng/mL, MTF 10 mM or the combination of IL-6 and MTF." (PMID 31337349, 2019). "Of note, IL-6 and IL-8 are overexpressed in TNBC compared to other breast cancer subtypes." (PMID 31394796, 2019). "A follow-up study with 534 patients demonstrated IL6, IL8, and IL10 may consider as indicators for poor prognosis and metastatic of breast cancer." (PMID 31398937, 2019).
breast cancer (continued). "PIM1 mRNA level was explored using quantitative PCR and we found that IL-6 could significantly elevate the mRNA of PIM1 in T47D and MCF7 breast cancer cells." (PMID 30989585, 2019). "Previous reported implied that IL-6 might link with the expression of PIM1 in pancreatic cancer cells and fibroblasts, and we observed this regulation pattern in breast cancer as well." (PMID 30989585, 2019). "IL-6/IL-6R antagonists as anti-breast cancer agents have not been broadly investigated and are even less studied in TNBC." (PMID 30885232, 2019). "Furthermore, OSM induces STAT3 phosphorylation and IL-1β promotes p65 phosphorylation to synergistically induce IL-6 secretion in ER− MDA-MB-231 and to a lesser extent in ER+ MCF7 human breast cancer cells." (PMID 31007849, 2019). "Both IL-6 and TNF-α are considered to be the best characterized tumorigenic cytokines that involved in the promotion, progression and metastasis of tumor, and also, co-expression of these two cytokines determines the extension and outcome of breast cancer." (PMID 31412862, 2019). "The IL-6/JAK1/STAT3 signaling pathway is also important and sufficient in the conversion of non-CSCs into CSCs through regulation of Oct4 expression in human breast cancer lines." (PMID 31557902, 2019). "IL-6 signaling was shown to cooperate with a hypoxic TME conditions to induce expression of C/EBPδ and other “stemness” promoting factors such as Nanog, Sox2 and Klf4 in breast cancer stem cells." (PMID 31450577, 2019). "Whether ANRIL expression correlates with IL6, CCL2, and POSTN in breast tumors was also investigated to provide evidence of how ANRIL may contribute to inflammation in breast cancer." (PMID 31572679, 2019). "In addition, the level of p‐STAT3 Y705 in breast cancer cells with SIRT4 transfection and IL‐6 treatment was higher than that in cells with SIRT4 transfection only." (PMID 31573734, 2019). "IL-6 and OPN were significantly enriched in WHF from surgeries for breast cancers ≥ 2 cm." (PMID 30791501, 2019). "We used the STRING bioinformatic tool to find biological processes associated with the gene products that we analyzed for their prognostic impact on breast cancer, namely IKKα (CHUK), IKBKB, p50/NFKB1, p65/RELA, NIK (MAP4K4), p52 (NFKB2), RELB, IL-8 (CXCL8), IL6, and MMP-1." (PMID 31602271, 2019). "To confirm the effects of adipocyte-derived IL-6 and leptin on the regulation of distal organ seeding and growth of metastatic tumor cells, we conducted tail vein metastasis assays using the MDA-MB-231 human breast cancer cell line." (PMID 30563531, 2018). "Additionally, recent evidence suggests that TNFα, IL-6, and TGFβ secreted from TCR-activated T cells induces EMT in inflammatory breast cancer cells." (PMID 29805773, 2018). "However, in our study we confirmed that IL-6 and leptin were responsible for the adipocyte-mediated upregulation of PLOD2 in breast cancer." (PMID 30563531, 2018). "These elevated circulating cytokines (IL-6, IL-8, TNF-α, and vascular endothelial growth factor; VEGF), exert effects at distant sites, that can promote breast cancer development through upregulation of inflammatory mediator synthesis and increased immune cell infiltration as well as angiogenesis." (PMID 30619088, 2018). "The results from blocking IL-6 signalling further confirmed our observation that the EMT-program is regulated by common and unique EMT-related gene expression patterns in different breast cancer cells." (PMID 29891854, 2018). "Transcriptional linear correlations between aromatase and the cytokines TNFα and IL-6 have been reported in patient breast cancer tissue, but not in adjacent non-cancerous tissue." (PMID 29463044, 2018). "SNAIL1 activates expression of CCL2, CCL5, IL-6, TNFα, and IL-8 in head and neck cancer cells and overexpression of SNAIL1 in 4T1 cells increased infiltration of M2-like macrophages and promoted metastasis in a breast cancer orthotopic model." (PMID 29593211, 2018).
breast cancer (continued). "Finally, we showed that IL-6 (5 ng/ mL) and leptin (50 ng/ mL) significantly increased the migration of MDA-MB-231 and MDA-MB-468 breast cancer cells." (PMID 30563531, 2018). "Based on the observation that adipocyte-derived IL-6 and leptin promoted PLOD2 expression in breast cancer cells, we next explored whether IL-6 and leptin activated JAK/STAT and AKT signals in vitro." (PMID 30563531, 2018). "Moreover, TNF-α, Interleukin-6 (IL-6), and TGF-β are related to epithelial-to-mesenchymal transition (EMT) in multiple cancers such as melanoma and breast cancer." (PMID 30139382, 2018). "Furthermore, IL6, IL-8, MCP-1, GRO-alpha, and VEGF were found to be maintenance and survival factors for bone metastatic breast cancer cells." (PMID 29867053, 2018). "Moreover, the secretion of IL-6 and leptin was significantly higher in the supernatant of MDA-MB-231 and MDA-MB-468 breast cancer cells after adipocyte coculture as compared with MDA-MB-231 and MDA-MB-468 cells grown alone." (PMID 30563531, 2018). "We found that a concentration of greater than 0.5 ng/mL of IL-6, 0.1 ng/mL of IL-12, and 1 ng/mL of IFN-γ dramatically suppressed B16F10 cell proliferation, whereas those cytokines had minimal effects on MMT, mammary tumor cells, and 3LL, which are lung carcinoma cells." (PMID 30042824, 2018). "Mechanistically, adipocyte-derived interleukin-6 (IL-6) and leptin may facilitate PLOD2 upregulation in breast cancer cells and promote breast cancer metastasis in tail vein metastasis assays." (PMID 30563531, 2018). "IL-6, VEGF, and TGF-β1 have been proved to be commonly overexpressed in human breast cancer cases, FGF10 played the important role in type III epithelial-mesenchymal transition (EMT) on breast cancer cells and initiation of metastasis, and high expression of FGF17 causes tamoxifen resistance." (PMID 29581982, 2018). "IL-6 potently promoted the amplification of e-MDSCs and their T cell-suppressive capacity in vitro by activating the STAT/IDO signaling pathway and generating a tryptophan-starved microenvironment that facilitated the evasion of breast cancer cells." (PMID 30083161, 2018). "On the other side, IL-6 is secreted also by adipose cells and may induce B-cell proliferation in the HER2-negative breast cancer lesions." (PMID 29394917, 2018). "Next, we investigated whether the IL-6-mediated cross-talk between DCIS.com and hPreAd was involved in breast cancer cell migration and proliferation." (PMID 30134951, 2018). "Furthermore, previous studies have shown both IL-6 and CCL2 are expressed in human breast cancer cell lines and enhance tumor growth, migration, and immune cell recruitment." (PMID 30458886, 2018). "Blocking IL-6 signalling did not reverse co-cultured breast cancer cells to their phenotype both MDA-MB-468 and MCF-7 cells remained slightly dispersed and elongated." (PMID 29891854, 2018). "In addition to IL-6, IL-8 and TGF-β, cytokines which can directly determine the effect of chemotherapy for breast cancer, also includes other factors such as M-CSF, TNFα, IL-1β and so on." (PMID 30175384, 2018). "Hence, blocking IL-6 signalling partially reversed the EMT phenotype and decreased the proliferation, migration and invasion characteristics of breast cancer cells." (PMID 29891854, 2018). "We next explored whether the expression of IL-6 and leptin receptors, which might mediate PLOD2 expression, was increased in MDA-MB-231 and MDA-MB-468 breast cancer cells after coculture with adipocytes." (PMID 30563531, 2018). "Thus, we concluded that the IL-6-related dysfunction of the SOCS3 feedback loop accelerated the growth and metastasis of mammary carcinoma by affecting myeloid differentiation and attenuating the T cell-based immune surveillance." (PMID 30083161, 2018). "Mammospheres enriched with stem/progenitor cells from node invasive breast carcinoma tissue expressed more IL-6 than matched non-neoplastic mammary glands." (PMID 30515368, 2018).
breast cancer (continued). "Treatment of breast cancer cells with doxycycline also decreased the translocation of NF-κB to the nucleus and the mRNA levels for IL-6 in the presence or absence of lysophosphatidate." (PMID 28178994, 2017). "Historically, the negative effect of IL‐6 on E‐cadherin expression in breast cancer cell lines was already demonstrated almost 20 years ago." (PMID 28599100, 2017). "We therefore investigated whether the positive influence of PTPRD on breast cancer cell stemness and EMT depends on IL-6/STAT3 signaling." (PMID 29228728, 2017). "In breast cancer tissues, IDO expression was correlated with IL-6 expression." (PMID 29296206, 2017). "In addition, we measured the concentrations of G-CSF, IL-1β, IL-6, CCL4 and TNFα in the plasma of the mice with breast cancer." (PMID 28178994, 2017). "However, upon treatment with honokiol (Group IV), mammary cancer bearing animals showed significant (p < 0.05) reversal in inflammatory cytokines levels of TNF-α, IL-1β, and IL-6." (PMID 28620301, 2017). "Furthermore, previous literature reported high circulating levels of IL6 and IL8 in patients with BM, and that patients suffering from pain with advanced breast cancer have high systemic levels of the inflammatory mediators TNF, IL-1b, and IL6." (PMID 28903357, 2017). "In our data set, no increased levels of IL-6 were detected in breast cancer, whereas in dense breast tissue the IL-6 levels were increased." (PMID 29387062, 2017). "In contrast, the expression of ZEB2 was generally low in breast cancer cells compared to THP‐1 cells, an acute myelogenous leukemia cell line with known ZEB2 function, and showed weaker correlation with IL6 and IL8 expression than that of ZEB1." (PMID 28618162, 2017). "Since luminal A breast cancer cell lines do not express IL6 or IL8, the relevance of these cytokines in CSC function has been poorly studied." (PMID 28472950, 2017). "Previous studies of breast cancer indicated that MDSCs express ADAM-family proteases and IL-6Rα, which contribute to breast cancer cell invasiveness and distant metastasis through the IL-6 trans-signaling pathway in murine models." (PMID 29326716, 2017). "Several studies have explored the independent negative impact of high levels of IL-6 or IL-8 on prognosis in patients with breast cancer." (PMID 29088874, 2017). "The autocrine secretion of IL-6 by tumor cells is also confirmed to contribute to chemo-resistance; further studies demonstrated that drug sensitive tumor cells do not or low express IL-6, yet, multidrug resistant breast cancer cells secreted more IL-6." (PMID 29296206, 2017). "In addition to its effect on constitutive TLR3, Wnt5a levels and subsequent IL-6 production and STAT3 levels/activation, we then evaluated the ability of C10 to inhibit the migration and viability/growth of MCF-7 breast cancer cells." (PMID 29371911, 2017). "Notably, IL-6 has been shown to contribute to proliferation and promote EMT and self-renewal in breast cancer cells establishing an essential communication between cancer cells and M2 TAMs." (PMID 28241877, 2017). "In addition, a previous study reported that IL-6 is a potent inducer of EMT, especially in breast cancer cells." (PMID 28208810, 2017). "A range of signaling mechanisms, including IL-6, IGF-1, leptin, and adiponectin, have been proposed to explain how mature adipocytes alter breast cancer cell behavior, but the role of adipocyte-derived fatty acids as direct metabolic substrates has not been investigated." (PMID 28101337, 2017). "In addition, JAG1, a potent downstream mediator of TGFB1, which promotes osteolysis in breast cancer cells by activating the NOTCH signaling pathway, leads to increased IL6 expression." (PMID 28319320, 2017). "Despite the well-established roles of SNPs within immune-related genes in breast cancer development and prognosis, there are no reports of the effects of IL-6: rs1800795 SNPs and breast cancer metastasis." (PMID 28732081, 2017).
breast cancer (continued). "Human primary mammospheres from node invasive breast cancers express higher levels of IL-6 than from mammospheres from matched nonneoplastic mammary glands." (PMID 29527228, 2017). "Interestingly, it has been recently shown, in models of advances breast cancers HER2+, that IL6 was expressed mainly by senescent cells." (PMID 28472950, 2017). "We identified a SNP in IL-6: rs1800795 to be of significance and evaluated this finding using a separate, matched-pair cohort of breast cancer patients with and without metastases from The Ohio State University Wexner Medical Center." (PMID 28732081, 2017). "Therefore, ZEB1 and ZEB2 have essentially similar functions in the regulation of inflammatory response gene expression, especially IL6 and IL8, in the basal‐type breast cancer cells." (PMID 28618162, 2017). "IL6 carries diverse regulatory roles in breast cancer pathogenesis including remodeling the microenvironment, activation of EMT process, malignant transformation, and modulating breast cancer stem cell activities." (PMID 28333977, 2017). "Treatment of luminal-type breast cancer cells with IL-1β did not induce IL-6 production in this study." (PMID 27609180, 2016). "In contrast to our expectations, simple overexpression of TG2 in otherwise TG2- and IL-6-negative luminal-type breast cancer MCF7 cells did not lead to IL-6 expression." (PMID 27609180, 2016). "Besides HCC cell lines, other cell types were tested in present study and IL-6 treatment also enhanced PGRN expression in lung, cervical and breast cancer cell lines, suggesting IL-6-driven PGRN expression is a common phenomenon." (PMID 26879559, 2016). "In the present study, the underlying mechanism by which IL-6 production is induced in luminal-type breast cancer cells was evaluated, and TG2 overexpression, IL-1β stimulation, and IL-6 expression were found to give cancerous cells a hormone-independent phenotype." (PMID 27609180, 2016). "We previously reported that IL-6 and transglutaminase 2 (TG2) were expressed in more aggressive basal-like breast cancer cells, and TG2 and IL-6 expression gave these cells stem-cell-like phenotypes, increased invasive ability, and increased metastatic potential." (PMID 27609180, 2016). "IL-6 has also been demonstrated as a Notch target gene in breast cancer cells, with the Notch-dependent activation of IL-6 reliant on IKKα/β function, but not on the canonical NF-κB signaling cascade." (PMID 27148486, 2016). "Among patients with breast cancer who were under treatment of coenzyme Q10 (100 mg/day) and vitamin B group (riboflavin 10 mg and niacin 50 mg), inflammatory markers included TNF-α, IL-8, IL-6, IL-1β were significantly decreased." (PMID 27047809, 2016). "The beneficial role of yoga has also been demonstrated in non-pregnant women, where an RCT study of breast cancer survivors showed a significant dose-response decrease in serum IL-1β and IL-6 in those who practiced yoga." (PMID 27348869, 2016). "However, IL-6 was profoundly elevated in the C3HBA tumor interstitial fluid, and treatment with the anti-IL-6 receptor antibody tocilizumab inhibited breast cancer growth." (PMID 27329584, 2016). "In this study, the effects of TG2 overexpression in luminal-type TG2 non-expressing breast cancer cells on IL-6 production and aggression were examined." (PMID 27609180, 2016). "STAT3 activation of target genes such as TGF-β1 and hypoxia inducible factor- (HIF-) 1α has been linked to EMT reprograming and several recent studies have shown that TAM-secreted IL-6, EGF, or MFGE-8 can activate STAT3 signaling in CSCs of breast cancer, HCC, or colon cancer." (PMID 26980947, 2016). "This increase appears to be breast cancer-specific since IL-6 levels were equal in serum and interstitial tissue of non-tumor bearing Chy and wt mice, and in KHT-1 tumors with or without the Chy mutation." (PMID 27329584, 2016).